SELENOWP1 (selenoprotein W pseudogene 1)
Synonyms: formerly SEPW1P
Gene: Processed pseudogene on chromosome 1 (31,094,987 to 31,095,558, reverse strand). Ensembl gene ENSG00000215900.
Diseases named in the same sentence as SELENOWP1 in open-access papers:
SELENOWP1 is named in the same sentence as 2 diseases in open-access papers, as found by Europe PMC text mining. Sharing a sentence is not in itself a finding about the gene and the disease.
SELENOWP1 shares sentences with these, for which no sentence is quoted: breast carcinoma (5 papers); cardiovascular diseases (1).